ASCL2 (achaete-scute family bHLH transcription factor 2)
Diseases named in the same sentence as ASCL2 in open-access papers (continued):
Sharing a sentence is not in itself a finding about the gene and the disease.
tumor (continued). "Meanwhile, ASCL2 might have an effect on tumor immune cell infiltration through an indirect mechanism by negatively regulating the expression of DUSP4." (PMID 35774798, 2022). "Activating TLR4 may recede the suppressive inflammatory factors expression, including NF-κB, IL-1β, and IL-18 by the ASCL2 regulation, and induce the inflammatory injury to tumor cells, thereby being involved in the prognosis of this disease." (PMID 36008864, 2022). "Previous studies have shown that ASCL2 can affect anti-tumor drug sensitivity." (PMID 35774798, 2022). "The level of ASCL2 in STAD tumor tissues is increased (P < 0.05)." (PMID 36008864, 2022). "The expression of the ASCL2 in tumor tissues is induced (P < 0.05)." (PMID 36008864, 2022). "Likewise, a vaccine against Ascl2 decreased the number of colon microadenomas in mice when administered prior to tumor formation, but had a minimal effect when given to mice with existing tumors." (PMID 34513688, 2021). "Furthermore, down-regulating ASCL2 decreased the tumorigenicity of GC cells, and tumor volume and weight were both reduced." (PMID 29805736, 2018). "Furthermore, Ascl2 expression in the tumor tissue from shRNA-Ascl2/HT-29 or shRNA-Ascl2/LS174T cells was significantly lower than that of shRNA-Ctr/HT-29 or shRNA-Ctr/LS174T cells, as determined by real-time PCR and western blot analysis." (PMID 22384170, 2012). "Next, to demonstrate the selective differentiation-inducing effect of VPA in tumor cells, we evaluated the expression of the CSC markers Sox9, Axin2, Cd44, and Ascl2 in organoids isolated from healthy mouse intestines." (PMID 40750758, 2025). "ASCL2 is the master regulator of intestinal stem cell fate, and CXCL8 is an inflammatory chemokine elevated in the CRC tumor microenvironment, playing a crucial role in promoting angiogenesis, invasion, and metastasis." (PMID 39456726, 2024). "Next, PGC-1α was overexpressed specifically in POU2F3/ASCL2 and ASCL1 PARCB tumor-derived cell lines, and its effects on OXPHOS activity and neuroendocrine differentiation were measured." (PMID 39589879, 2024). "This analysis revealed that PARCB-ASCL1 tumor-derived cell lines showed significantly higher basal and maximal oxygen consumption rates compared to the POU2F3/ASCL2 subtype, indicating increased OXPHOS activity." (PMID 39589879, 2024). "Together, these results suggested that Ascl2 inhibition potentiated the ability of anti-PD-L1 to enhance antitumor immunity, resulting in optimal CD8+ T cell positioning and ensuing tumor regression." (PMID 37591954, 2023). "Compared with the ApcMin/+;Ascl2 CKO mice, ApcMin/+ mice displayed more activated CAFs and reduced tumor-infiltrating CD8+ T cells, leading to a tumor suppressive immune microenvironment." (PMID 37591954, 2023). "ASCL2 is overexpressed in pMMR/MSS CRCs and maintains a stemness phenotype, accompanied by a lower density of tumor-infiltrating lymphocytes (TILs) than those in dMMR/MSI CRCs." (PMID 37591954, 2023). "In our study, sh-ASCL2 can inhibit STAD development by increasing apoptosis and reducing proliferation, tumor volume, and biomarker levels." (PMID 36008864, 2022). "The results of the study indicate that si-Ascl2 (small/short interference) exerts a tumor suppressor function in CRC by inducing autophagic cell death, and indicates that Ascl2 targeted therapy represents a new strategy for the treatment of CRC." (PMID 35836256, 2022). "Strikingly, markers of normal colon stem cells (LGR5, ASCL2, SOX9), were also strongly downregulated EHFlow CRC cells, suggesting that these lines give rise to tumours that are de-differentiated to the point of losing their colonic identity." (PMID 35606410, 2022). "In conclusion, this study identifies ASCL2 as a specific master TF in CRC with MSS status, whose presence is significantly negatively correlated with IFN-γ and IFN-α responses in the tumor microenvironment." (PMID 33628843, 2021).
tumor (continued). "Upon treatment of these tumours with anti-RSPO3 antibody using patient-derived xenograft models, expression of LGR5 and ASCL2 were highly downregulated, whereas MYC, AXIN2 and CCND1 (cyclin D1) did not rank among the top 100 downregulated genes." (PMID 30792270, 2019). "ASCL2/MYC tumours displayed the lowest immune infiltration, in contrast to the highly inflamed tumours of the ECM/EMT group showing a maximal tumour purity of 50%." (PMID 28186126, 2017). "Although a few sensitive tumours belonged to the ECM/EMT group, those were showing similarities with the ASCL2/MYC samples (subgroup A)." (PMID 28186126, 2017). "On the basis of this performance, we applied the OT mini-classifier to the original OT-patient cohort, predicting that sensitive cases were mainly found in the ASCL2/MYC group, in particular early stage tumours (Fisher's exact test P=0.0068)." (PMID 28186126, 2017). "Importantly, reduced mRNA expression of LGR5, OLFM4, ASCL2 and EPHB2 was also observed in HG primary tumours in the TCGA dataset." (PMID 40473896, 2025). "Further, PGC-1α expression markedly increased in the majority of tumor series derived from distinct donor tissue series, with a sudden drop in PGC-1α expression levels in two patient series (P3 and P10) upon development of the POU2F3/ASCL2 subtype." (PMID 39589879, 2024). "In addition, the genes characterizing classical phenotypes of cancer stem-like (ASCL2), hypoxia (WSB1) and apoptosis (ATF3) were all highly expressed in the tumor or stromal region, suggesting cell differentiation programs." (PMID 38729966, 2024). "Furthermore, deletion of Ascl2 eliminated the ability of CAFs to decrease tumor-infiltrating CD8+ CTLs in the C57BL/6 J and Ascl2 CKO mice." (PMID 37591954, 2023). "Sh-ASCL2 could reduce STAD development by decreasing proliferation, tumor volume, and biomarker levels and increasing apoptosis in vitro and in vivo." (PMID 36008864, 2022). "Moreover, ASCL2 was highly expressed in COAD compared with HOXC6 and APCDD1 in multiple tumor types." (PMID 35774798, 2022). "Further studies are required to understand how ASCL2 regulates IFN-γ and IFN-α responses within the tumor microenvironment, which might prevent the immune evasion and improve the effect of immunotherapies in MSS CRC patients." (PMID 33628843, 2021). "Studies have shown that abnormal expression of ASCL2 can enhance the invasion and metastasis of CRC cells in vitro; that overexpression of ASCL2 correlates with distant metastasis, tumor size and poor overall survival in CRC patients; and that high expression of ASCL2 promotes EMT in CRC." (PMID 29805736, 2018). "Moreover, restoring ASCL2 or CPT1A expression in FAT1 KO SCC1 cells not only counteracted the reduction in cell proliferation and clonogenicity mediated by FAT1 KO, but also reversed the inhibition of tumor growth in an orthotopic mouse model." (PMID 40407216, 2025). "Specific genes downregulated in HG tumours which showed significantly higher promoter methylation included the developmental transcription factors CDX1, CDX2, GATA6, HNF1A, the marker of colonic differentiation, DPP4, and the markers of LGR5+ intestinal stem cells, ASCL2, LGR5." (PMID 40473896, 2025). "Moreover, a transgenic mouse model revealed that ectopic overexpression of ASCL2 does not increase tumor initiation or progression." (PMID 37591954, 2023). "Moreover, Ascl2 had no apparent effect on the tumor growth of MC38 tumors established in T cell-deficient nude mice, suggesting the critical role of T cells in the Ascl2-induced antitumor effect." (PMID 37591954, 2023).
tumor (continued). "Ascl2 further indicated that its expression was enhanced in benign and malignant neoplastic diseases of the large intestine, and its expression alters the hierarchy of stem cells within liver metastases, leading to self-renewal rather than differentiation, thereby affecting tumor clinical behavior." (PMID 36824410, 2023). "Together, these results showed that the expression of ASCL2 and ETV4 had negative correlation with T cell infiltration in the tumor microenvironment, indicating that overexpression of ASCL2 and ETV4 might inhibit the recruitment and activation of CD8+ T cells in MSS CRC patients." (PMID 33628843, 2021). "Although a humoral response against the transcription factor Ascl2 was not expected, our results demonstrate the capacity of our vaccine platform to promote a strong humoral response, which is of great interest for developing vaccines against tumor surface antigens, such as Epcam or CEACAM5." (PMID 33671373, 2021).
cancer (39 papers, 2008 to 2025). A tumor composed of atypical neoplastic, often pleomorphic cells that invade other tissues. "LeuAAG-001-N-3p-68-85 was validated to target UPF1, a regulator of mRNA decay, while AlaAGC-002-N-3p-58-75 was linked to the suppression of ASCL2, a transcription factor involved in cancer progression." (PMID 40981380, 2025). "As an indispensable downstream element of Wnt/β-catenin signaling pathway, ASCL2 is closely associated with the occurrence and development of different cancers." (PMID 40963862, 2025). "Frequency of CD44+ cells and expression levels of Cd44 and other cancer stem cell markers Ascl2, Lgr5 and Smoc2 were markedly reduced in Mex3a-deficient tumors." (PMID 36276637, 2022). "Noticeably, ISC and TA marker ASCL2, were universally expressed in all undifferentiated cells, which also agreed with the highly proliferative phenotype of cancer cells." (PMID 38523788, 2024). "The Wnt target gene ASCL2 was prominently higher in tumors than in adjacent normal tissues through analyzing both TCGA (The Cancer Genome Atlas) and GEO databases, suggesting a role for abnormal ASCL2 expression in the etiology of colorectal tumorigenesis." (PMID 37591954, 2023). "These are worthwhile to point out that CST1, CHI3L1, UBD, and INHBA genes were verified by the GEPIA in both COAD and READ cancer types while ASCL2 was verified only in COAD cancer type by the GEPIA." (PMID 35333898, 2022). "Immediately, we analyzed the expression of the top three genes, which tie for first place (HOXC6, APCDD1, and ASCL2) in multiple cancer types to explore possible roles of the genes in carcinogenesis." (PMID 35774798, 2022). "SMYD3 has been reported to function in key pathways for self-renewal and tumorigenicity of GC stem cells through activation of the cancer stem cell transcription factor ASCL2." (PMID 33637115, 2021). "Additional transcriptional targets of PLAGL2 (e.g., MPL and ASCL2) were found in other cancer cell types." (PMID 32087738, 2020). "An example of another candidate bHLH tissue biomarker is ASCL2, a transcription factor involved in tumoral progression that exhibits high abnormal expression in progressive cancer." (PMID 32708589, 2020). "The cancer tissue-based eQTL analysis in three independent datasets also showed the increased expression of ASCL2 in patients with haplotype A–A–A." (PMID 29789573, 2018). "Now we demonstrated that CD133+/CD44+ cell population from HT-29 or Caco-2 cells exhibited cancer stem cell (CSC) properties with highly expressed Ascl2, which is related to the Hippo signaling pathway." (PMID 29312609, 2017). "DNA hypermethylation of the transcription factor ASCL2 has been identified in other cancers and is involved in the regulation of gene expression in the central and peripheral nervous system." (PMID 24650279, 2014). "Therefore, we investigated the contribution of ASCL2 to another key characteristic of stem cells, resistance to anti-cancer treatments." (PMID 38252116, 2024). "Furthermore, overexpression of ASCL2 was associated with increased TGFB levels, which stimulate local Cancer-associated fibroblasts (CAFs) activation, inducing an immune-excluded microenvironment." (PMID 37591954, 2023). "Notably, ASCL2 and DUSP4 had the highest association with MSI in COAD compared to the other cancer types." (PMID 35774798, 2022). "ASCL2 was highly expressed in cancer stem cells (cluster 4)." (PMID 35774798, 2022). "In addition, ASCL2 plays a significant role in microsatellite instability status, cancer stemness, and immune cell infiltration of COAD." (PMID 35774798, 2022). "Moreover, we classified all cancer samples (in each cancer type) in TCGA based on the RNA expression of ASCL2." (PMID 33628843, 2021). "Notably, among all cell lines in CCLE, MSS CRC cell lines have the highest ASCL2 expression, which also reminds that ASCL2 might play important roles in this cancer type." (PMID 33628843, 2021).
cancer (continued). "Notably, MSS CRC cell lines had the highest expression of ASCL2 among all human cancer cell lines." (PMID 33628843, 2021). "Therefore, the question arose as to whether there is any relation between bufalin-mediated anti-cancer activity and ASCL2 expression." (PMID 29805736, 2018). "To corroborate this, we assessed the expression levels of genes in AP-1, NF-κB, ASCL2, and LEF1 regulons across the cancer states." (PMID 40393458, 2025). "The results revealed that ASCL2 was highly correlated to the infiltration levels of CD4+ T cells, CD8+ T cells, B cells, neutrophils, and dendritic cells in the vast majority of cancer types." (PMID 35774798, 2022). "In our study, we found that RAI2 suppressed the expression of ASCL2 and LGR5 by Western blot in CRC cells, and we also found a negative correlation between RAI2 and ASCL2/LGR5 in 298 cases of cancer tissues from CRC patients by IHC detection." (PMID 35299743, 2022). "The expression of ASCL2 was significantly correlated with the infiltration levels of CD4+ T cells, CD8+ T cells, B cells, neutrophils, and dendritic cells in various cancer types, including COAD." (PMID 35774798, 2022). "We found that high CCNP expression correlated with a high expression of Axin2 (p < 0.0001), cyclin D1 (CCND1) (p = 0.0026), Lgr5 (p < 0.0001) and Ascl2 (p < 0.0001), suggesting that CCNP and stemness are broadly intertwined in human cancer." (PMID 34604945, 2021). "In the meanwhile, this study identified ASCL2 as a master regulator in MSS CRC using bioinformatic approach based on the published datasets (GI cancer ChIP-Seq data and TCGA pan-cancer RNA-Seq data)." (PMID 33628843, 2021). "Considering that ASCL2 and ETV4 are upregulated in MSS CRC tissues in TCGA, we next investigated the expression of ASCL2 and ETV4 in MSS CRC cell lines and compared their expression with other cancer cell lines." (PMID 33628843, 2021). "Although the expression of ASCL2 is negatively correlated with IFN-γ and IFN-α response pathways in several cancer types, COAD MSS samples have the highest expression of ASCL2 among these cancer types." (PMID 33628843, 2021). "Cancer stem cells are supposed to be resistant to the various anti-cancer therapies and an obstacle against treatments, and stem cell biomarkers have been identified such as CD44, CD133, Ascl2, and Lgr5 in CRC." (PMID 37098074, 2023). "Furthermore, qRT-PCR results from our specimens verified an over-expression of ASCL2, CREB3L3, and MFAP2 in the cancer cells compared with the normal cells." (PMID 36936373, 2023). "In the present study, ASCL2 expression was significantly correlated with the infiltration levels of CD4+ T cells, CD8+ T cells, B cells, neutrophils, and dendritic cells in various cancer types, including COAD." (PMID 35774798, 2022). "Therefore, we determined the correlation between the expression of ASCL2 and DUSP4 with MSI in 32 cancer types." (PMID 35774798, 2022). "Analyses of transcripts altered in TMED3 kd cells over control levels revealed a group of 63 RNAs enhanced twofold or more that included several genes previously shown to promote pro-metastatic behavior in different cancers, including SOX8, ASCL2, FGF19, and CXCR4." (PMID 31253868, 2019). "All tuft cell-like cancers identified in this way also strongly expressed other tuft cell-markers, such as TRPM5, SOX9, ASCL2, and AVIL but not CHAT." (PMID 36402755, 2022).
infection (3 papers, 2018 to 2025). The state of being infected such as from the introduction of a foreign agent such as serum, vaccine, antigenic substance or organism. "We use this system to define the necessity of the chemokine receptor CXCR3 and the migration-associated factor ASCL2 in the enrichment of NK cells in the splenic white pulp after infection." (PMID 40694683, 2025). "Infection triggered a statistically significant increase in the number of Ascl2 WT donor NK cells present within the white pulp or T cell zones compared to uninfected mice." (PMID 40694683, 2025). "We intravenously transferred splenic CD45.2+ NK cells from either Ascl2 cKO or Ascl2 WT mice into JAXBoy mice 3 d before infection with LCMV Armstrong." (PMID 40694683, 2025). "(I) Western blot of Ascl2 and Lgr5 showing IL-17 antibody-abrogated C. rodentium-infection-induced colon stem cell marker expression." (PMID 30543324, 2018). "We hypothesized that NK cells may require ASCL2 for precise localization to subdomains of lymphoid tissues during infection (ie, infiltration of white pulp)." (PMID 40694683, 2025). "In contrast, Ascl2 cKO NK cells were not enriched in the white pulp or T cell zones after infection." (PMID 40694683, 2025). "The induction of Lgr5 was fairly specific, as other gastric stem cell markers, such as Sox2, Troy, Runx1, Lrig1, and others were not induced as a consequence of infection; an exception was Ascl2, the expression of which mirrored that of Lgr5." (PMID 39191487, 2024).
ASCL2 also shares sentences with these, for which no sentence is quoted: colon (2 papers); polyp (2); Autoimmunity (1); basal cell carcinoma (1); breast tumors (1); colon polyps (1); COVID-19 (1); embryonal carcinoma (1); ependymoma (1); gastroesophageal reflux (1); hydatidiform mole (1); infectious disease (1); liver cancer (1); lung adenocarcinoma (1); medulloblastoma (1); neuroblastoma (1); neurodegenerative disease (1); overgrowth syndrome (1); Pan (1); preeclampsia (1); sarcoma (1); Sjögren syndrome (1); stomach adenocarcinoma (1); testicular cancer (1).